SNORD31B (small nucleolar RNA, C/D box 31B)
Gene: Small nucleolar RNA gene on chromosome 13 (107,320,895 to 107,320,963, reverse strand). Ensembl gene ENSG00000201847.
Gene Ontology:
Biological process: RNA processing
Cellular component: nucleolus
Homologues: Orthologues: chimpanzee SNORD31 (100% identical), macaque SNORD31 (93% identical), dog SNORD31 (84% identical), pig SNORD31 (81% identical), guinea pig SNORD31 (80% identical), rabbit SNORD31B (80% identical), mouse Gm23246 (75% identical), rat LOC120100232 (74% identical), tropical clawed frog SNORD31 (67% identical), tropical clawed frog SNORD31 (64% identical), zebrafish snord31.1 (61% identical), zebrafish snord31.3 (61% identical), and 2 more.